MX2 (MX dynamin like GTPase 2)
Diseases named in the same sentence as MX2 in open-access papers (continued):
Sharing a sentence is not in itself a finding about the gene and the disease.
melanoma (22 papers, 2014 to 2026). A malignant, usually aggressive tumor composed of atypical, neoplastic melanocytes. "It was shown that the level of MX2 expression is critically mediated by YY1 further underlying the role of YY1 in melanoma." (PMID 35719931, 2022). "MX2 rs45430 had nominal associations with log of Breslow thickness, presence of mitoses, and melanoma-specific survival." (PMID 34898573, 2021). "Until recently, Choi and colleagues found the imperative role of MX2 in melanoma susceptibility through an integrative approach." (PMID 34306023, 2021). "We have previously demonstrated that MX2 is also associated with the tumorigenesis process in melanoma." (PMID 33734579, 2021). "Previously reduced risk of melanoma has been correlated to a SNP (rs45430) intronic to interferon response MX2 (myxovirus resistance 2) gene in genome‐wide association studies." (PMID 33734579, 2021). "Our integrative approach streamlines GWAS follow-up studies and highlights a pleiotropic function of MX2 in melanoma susceptibility." (PMID 32483191, 2020). "Through molecular interrogation, we demonstrated that a melanoma-associated intronic variant, rs398206, contributes to allelic expression of MX2 via modifying an enhancer element recruiting the transcription factor, YY1." (PMID 32483191, 2020). "Together these data determined that rs398206 is a functional variant regulating MX2 expression via differential YY1 binding in the Chr21q22.3 melanoma locus." (PMID 32483191, 2020). "rs398206 was also a significant eQTL for levels of MX2 gene expression in primary melanocytes, where the melanoma risk-associated A allele is correlated with higher MX2 expression (Slope = 0.70, P = 6.6e−15; linear regression)." (PMID 32483191, 2020). "Together these data are consistent with MX2 expression contributing to an increased melanoma risk, however consistent with in vitro data, likely through a mechanism other than increased cell proliferation." (PMID 32483191, 2020). "Our zebrafish model provided further support for MX2 as a melanoma susceptibility gene accelerating melanoma formation when expressed in the cells of melanocytic-lineage." (PMID 32483191, 2020). "Interestingly, we identified the same SNP as an eQTL that downregulates MX2 in sun‐exposed skin, consistent with another study that suggested a tumor‐supressive feature of MX2 where its downregulation was associated with melanoma disease progression." (PMID 38308491, 2024). "Finally, recently published data of genome wide association study identified about 20 melanoma susceptibility loci, one of which was MX2 – the HIV-1 restriction gene." (PMID 35719931, 2022). "Also noteworthy are the results that the melanoma-risk MX2 rs45430*A allele was positively associated with increased Breslow thickness, presence of mitoses, and worse melanoma-specific survival in GEM." (PMID 34898573, 2021). "Interestingly, it should be noted that MX2 overexpression also led to a significant decrease of DSG2 expression which has previously been associated with unfavorable melanoma outcome." (PMID 33734579, 2021). "Furthermore, MX2 is found downregulated during disease progression and associated with melanoma‐specific patient survival." (PMID 33734579, 2021). "meQTL analysis, on the other hand, identified a significant meQTL for rs398026 at a CpG probe near the MX2 canonical promoter, where the melanoma risk-associated A allele is correlated with lower CpG methylation, which is consistent with higher expression of the full-length isoform." (PMID 32483191, 2020). "To begin to understand what genes and pathways might be affected by increased MX2 expression and could potentially underlie the altered melanoma cells/melanocytes growth, we performed RNA-seq analyses on melanocytes over-expressing MX2 (2–10-fold induction at 72 h)." (PMID 32483191, 2020). "MX2 contributes to the innate immune defense against viruses and regulates cell-cycle progression in melanoma." (PMID 40971676, 2025).
melanoma (continued). "Among the genes we identified, many are known melanoma susceptibility genes including CASP8, ARNT, and OCA2 (downregulated), PARP1, SETDB1, MTAP, SLC45A2, and MC1R (upregulated), and MX2 (both up‐ and downregulated)." (PMID 38308491, 2024). "Apart from the interferon-associated mechanism that regulates angiogenesis, CM from miR193a-3p-transfected MCF-7 cells also down regulated MX2, a dynamin-like GTPase and cell cycle regulator, which has been shown to induce growth in a subset of melanoma cells." (PMID 36230929, 2022). "Regarding MX2 protein, overexpression of MX2 in primary melanoma reduces in vivo proliferation partially through inhibition of AKT activation." (PMID 34361872, 2021). "They further found that melanocyte-specific expression of human MX2 in a zebrafish model accelerated melanoma formation in a BRAFV600E background." (PMID 34898573, 2021). "Previously, it has been reported that MX2 overexpression leads to growth inhibition of melanoma cells in a cell type‐specific manner." (PMID 33734579, 2021). "Our RNA‐seq analysis revealed XAF1 as one of the top candidate genes induced by MX2 overexpression, which was also observed in several other melanoma cell lines and primary human melanocytes engineered to overexpress MX2." (PMID 33734579, 2021). "We have reported that MX2 has tumor‐suppressive activity and is downregulated during the progression of melanoma." (PMID 33734579, 2021). "While MX2 overexpression renders melanoma cells less proliferative, previously, it has been shown that activation of the IFN pathway and higher XAF1 expression are associated with increased cell sensitivity to cytotoxic treatments." (PMID 33734579, 2021). "To identify downstream effectors and molecular mechanisms mediating MX2 tumor growth suppression, we performed RNA‐seq of MX2 overexpressing WM983b melanoma cells." (PMID 33734579, 2021). "Investigation of additional constitutively MX2‐/GFP‐overexpressing melanoma cell lines and normal human melanocytes with doxycycline induced MX2/GFP expression showed similar results." (PMID 33734579, 2021). "Higher MX2 expression renders melanoma cells more sensitive to targeted therapy drugs such as vemurafenib and trametinib; however, this effect is XAF1 independent." (PMID 33734579, 2021). "We also examined XAF1 mRNA and protein expression in melanocytes and melanoma cell line panel previously investigated for MX2 expression." (PMID 33734579, 2021). "Jointly, these results provide further explanation why MX2 expression is a predictor of better patient survival in melanoma." (PMID 33734579, 2021). "It is possible that MX2 downregulation is a result of frequently observed downregulation of interferon signaling in melanoma that ultimately can result in reduced immune cell recruitment and immune recognition of tumor cells." (PMID 33734579, 2021). "Using our approach we identify a functional risk variant that increases the level of an HIV-1 restriction gene, MX2, in cells of melanocytic lineage; subsequent expression of MX2 in melanocytes of a zebrafish melanoma model accelerates melanoma formation." (PMID 32483191, 2020). "Here, using a massively parallel reporter assay, the authors identify risk-associated variants that alter gene transcription, and demonstrate that expression of one such gene, MX2, leads to the promotion of melanoma in a zebrafish model." (PMID 32483191, 2020). "Further studies will be required to tease out the discrepancy between single cell-type assay and zebrafish model, as well as the molecular mechanisms of how MX2 contributes to melanoma promotion." (PMID 32483191, 2020). "It is possible that the effect of increased MX2 levels have roles only in specific contexts during the process of melanoma development." (PMID 32483191, 2020). "Melanocyte-specific expression of human MX2 in a zebrafish model demonstrates accelerated melanoma formation in a BRAFV600E background." (PMID 32483191, 2020).
melanoma (continued). "Our findings suggest a role of MX2 in promoting melanoma formation when exclusively expressed in cells of melanocytic-lineage, in the presence of BRAFV600E, a frequent somatic driver mutation." (PMID 32483191, 2020). "Genes of special interest previously associated with various types of cancer where the SMAD6 and SOCS3 genes coupled to aggressive kidney cancer, and the MX2 gene with suggested role in melanoma pathogenesis." (PMID 30642274, 2019). "The results also included 10 SNPs previously identified for melanoma risk reported at MC1R (2 SNPs), MX2, TERT/CLPTM1L, PLA2G6, CASP8, ACTRT3, ASIP, CDC91L1, and ARNT/SETDB1/LASS2ANXA9/MCL1/CTSK." (PMID 27993549, 2017). "MX2 (MX dynamin-like GTPase 2) is a novel regulator of cell cycle in melanoma cells." (PMID 35619698, 2022). "In addition to mediating growth‐inhibitory effects of IFN, MX2 expression increased the sensitivity of melanoma cells to MAPK pathway inhibitors." (PMID 33734579, 2021). "Collectively, our data suggest that XAF1 might be partially mediating MX2 growth effects in melanoma tumors as well." (PMID 33734579, 2021). "However, in addition to being reported as a tumor suppressor in glioblastoma and melanoma, lately, the function of MX2 in tumors and anticancer drug-related resistance has been rarely discussed." (PMID 34306023, 2021). "In this study, we have investigated molecular mechanisms regulated by MX2 in melanoma." (PMID 33734579, 2021). "Moreover, we have previously demonstrated that MX2 overexpression suppresses growth of melanoma cells and tumors partially by reducing the AKT pathway activity 5 and results presented here suggest that XAF1 contributes to this regulation." (PMID 33734579, 2021). "Interestingly, here, we show that MX2 overexpression contributes to the establishment of an IFN signature in melanoma cells and that MX2 is involved in IFN regulatory networks." (PMID 33734579, 2021). "MX2 rs45430*G had nominal associations with decreased log of Breslow thickness and absence of mitoses, as well as better melanoma-specific survival." (PMID 34898573, 2021). "MX2 upregulation establishes an interferon‐induced transcriptional profile in melanoma cells." (PMID 33734579, 2021). "Interestingly, we showed that in melanoma cells, MX2 mediates growth‐inhibitory effects of IFNα in a highly cell‐specific manner either via XAF1 or XAF1 independently." (PMID 33734579, 2021). "However, in a subset of melanoma cell lines with high endogenous MX2 expression where downregulation of MX2 leads to reduced proliferation." (PMID 34361872, 2021). "However, it is still unclear what role MX2 has in IFN response in melanoma and through which molecular mechanism these effects are exerted." (PMID 33734579, 2021). "To test this idea and establish a melanocyte-specific role for MX2 expression in the development or progression of melanoma, we examined transgenic expression of human MX2 in a zebrafish melanoma model, in conjunction with the most recurrent somatic driver event of melanoma, BRAFV600E." (PMID 32483191, 2020). "siRNA knockdown of YY1 in the UACC903 melanoma cell line demonstrated a weak but consistent reduction of MX2 levels by four different sets of siRNAs (14–32% decrease, P = 1.5e−3–1.9e−5, one-sample Wilcoxon test) indicating a regulation of MX2 levels by YY1." (PMID 32483191, 2020). "A recent study also reported that MX2 over-expression resulted in decreased growth in primary melanocytes and melanoma cells, while the effect could be the opposite in a subset of melanoma cells." (PMID 32483191, 2020). "Given the possibility of a melanocyte-specific function of MX2, we hypothesized that melanocyte-specific MX2 expression might have roles in early events of melanoma formation." (PMID 32483191, 2020).
melanoma (continued). "The results demonstrated that zebrafish with transgenic human MX2 expression presented an accelerated melanoma formation (46% of fish developed melanoma by 19 weeks; n = 184) compared to those with GFP controls (33% of fish by 19 weeks; n = 194) in this genetic background (P = 0.003; log-rank test)." (PMID 32483191, 2020). "To test this hypothesis, we first asked if MX2 affects growth of primary melanocytes and melanoma cells in a single culture system." (PMID 32483191, 2020). "In addition, MX2 may also modulate XAF1 to increase the sensitivity of melanoma cells to targeted therapies, which may be related to immune responses." (PMID 36059547, 2022). "Interestingly, these authors found the effects of MX2 expression on melanoma proliferation were context-dependent, with high expression in primary melanoma cell lines and melanocytes suppressing tumorigenesis, while downregulation in a subset of melanoma cell lines reduced proliferation." (PMID 34898573, 2021). "MX2 regulates tumor suppressor XAF1 and sensitizes melanoma cells to targeted therapy drugs such as vemurafenib and trametinib." (PMID 33734579, 2021). "MX2 and XAF1 expression tightly correlate in both cultured melanoma cell lines and in patient‐derived primary and metastatic tumors, where they also are significantly related with survival." (PMID 33734579, 2021). "We observed a strong correlation between MX2 and XAF1 in the primary melanomas, while in metastatic tumors from this correlation was weaker, although still significant." (PMID 33734579, 2021). "We also show that MX2 mediates IFN inhibitory effects in melanoma, sensitizes melanoma cells to MAPK pathway targeted therapy, and regulates XAF1 that has prognostic impact in melanoma patients." (PMID 33734579, 2021). "To further determine if the genomic region encompassing rs398206 regulates endogenous MX2 levels, we targeted this region by CRISPRi using dCAS9-KRAB-MeCP238 in the same melanoma cell line." (PMID 32483191, 2020). "Juraleviciute and their colleagues noticed that the MX2 could regulate the XAF1 and make the melanoma cells sensitive to targeted therapy." (PMID 37063301, 2023). "Since we here have identified XAF1 as an effector downstream of MX2, and XAF1 has previously been shown to inhibit tumor growth and mediate apoptotic effects in several cancers, we asked if XAF1 can have a similar function in melanoma cells." (PMID 33734579, 2021). "Considering that IFN signaling defects are shown to contribute to immunotherapy resistance in melanoma patients, re‐establishing and enhancing the IFN signature in tumor cells via reactivation of regulators like MX2 might improve clinical responses." (PMID 33734579, 2021). "MX2 is an IFN response gene, and IFN signaling is frequently downregulated in melanoma 6 which could explain previously observed reduction of MX2 in melanoma samples." (PMID 33734579, 2021). "We further performed histopathology analyses of zebrafish melanomas and did not observe gross difference in tumor morphology and invasion between MX2 and GFP groups." (PMID 32483191, 2020). "On the other hand, an examination of immune infiltrates in melanomas from TCGA did not provide sufficient evidence for the roles of MX2 in tumor immune surveillance other than weak correlations with infiltration of a few cell types." (PMID 32483191, 2020). "B16F1 mouse melanoma cells harboring the HyBNAR construct specifically bound Hu-IFN-Is and were rendered sensitive to Hu-IFN-I stimulated anti-proliferation, STAT1 activation and activation of a prototypical IFN-I response gene (MX2)." (PMID 24416207, 2014). "Therefore, in our study, we chose c‐MYC as a loading control for nuclear fraction of proteins, since it shows nuclear distribution and is not affected by MX2 downregulation in melanoma cells." (PMID 33734579, 2021).
melanoma (continued). "In this study, we aimed to elucidate the molecular mechanisms and networks affected by the antiviral MX2 gene, previously reported to have tumor‐suppressive features in melanoma partially through negative modification of AKT activity, cell cycle, and tumor growth." (PMID 33734579, 2021). "Our zebrafish tumor proliferation assay also suggested that accelerated melanoma formation by MX2 might not be due to increased proliferation per se." (PMID 32483191, 2020). "Not much information is available concerning MX1 and MX2 during SARS-CoV-2 infection; however, in melanoma cell lines, it was reported that persistent IFN-γ stimulation increases the expression and genome occupancy of STAT1 and induces the expression of ISGs, such as IFIT1 and MX1." (PMID 36298734, 2022). "However, even though we did observe an upregulation of XAF1 following MAPK pathway inhibition in melanoma cells, XAF1 downregulation did not affect responses to the drugs indicating that MX2 sensitization is achieved independent of XAF1." (PMID 33734579, 2021).
COVID-19 (12 papers, 2021 to 2025). A disease caused by infection with severe acute respiratory syndrome coronavirus 2. "An abnormal type I interferon (IFN) response is exhibited with the COVID-19 patients, which results in the deregulation of interferon-stimulated genes(ISGs) including MX2 and leads the COVID-19 severity." (PMID 36949176, 2023). "Since MX1, MX2, ISG15, and OAS1 showed a similar expression pattern in COVID-19-positive patients, we next evaluated the association of their combined expressions with viral load." (PMID 36298734, 2022). "Although the expression of MX1 and MX2 in patients with COVID-19 were significantly higher than those in non-COVID-19 groups, MX1 shows a greater positive correlation with patients with COVID-19 and may be more specific than MX2 in response to SARS-CoV-2." (PMID 35620480, 2022). "As an indication of disease severity, we measured the mRNA expression levels of IFN-stimulated genes (IFIT1, IFIT3, ISG15, and MX2), pro-inflammatory cytokines (IL6, IL10), and chemokines (CXCL10, CCL2) that are correlated with COVID-19 exacerbation." (PMID 35562337, 2022). "The MX2 gene is highly enriched in the type 1 interferon signaling pathway, which plays a crucial role in the development of IPF disease and the innate immune response in the pathogenesis of COVID-19." (PMID 39024368, 2024). "Furthermore, results evidenced that COVID-19-positive patients with higher expressions of JAK2 and STAT1 showed increased MX1, MX2, ISG15, and OAS1 mRNA levels." (PMID 36298734, 2022). "Expression of MX1, MX2, ISG15, and OAS1 (four well-known IFN-stimulated genes (ISGs)) displayed upregulation in COVID-19-positive vs. -negative patients." (PMID 36298734, 2022). "Notably, in the present work, we demonstrated that the expressions of the ISGs MX1, MX2, ISG15, and OAS1 were upregulated in COVID-19-positive vs. -negative patients." (PMID 36298734, 2022). "The expression of MX1, MX2, ACE2, and BSG/CD147 can cluster individuals with and without COVID-19 through principal component analysis, which indicated that the expression levels of MX1 and MX2 between patients with and without COVID-19 are remarkably different." (PMID 35620480, 2022).